CCL2 (C-C motif chemokine ligand 2)
Diseases named in the same sentence as CCL2 in open-access papers (continued):
Sharing a sentence is not in itself a finding about the gene and the disease.
breast cancer (continued). "Overall, CCL2 enhances breast cancer cell migration, proliferation, and survival through MET-dependent mechanisms." (PMID 35405500, 2022). "LncRNA associated with breast cancer brain metastases (lnc-BM) is significantly upregulated in brain metastasis and influences TAM recruitment by inducing the production of CCL2 via JAK2/STAT3 pathway activation in cancer cells." (PMID 35202089, 2022). "Breast cancer can be treated with CCL2 neutralizing antibodies and the same outcomes were observed by targeting CCR2." (PMID 36403055, 2022). "In mice bearing late-stage MMTV-PyMT mammary tumors with spontaneous metastasis, treatment with CCL2 inhibitors reduced metastasis through diminished recruitment of metastasis-associated macrophages." (PMID 35435599, 2022). "CCL2 has been found to play a crucial role in the growth, metastasis, and invasion of breast cancer cells in recent research." (PMID 36403055, 2022). "By cooperating with DNMT1, EZH2 knockdown led to DNA demethylation and consequently upregulated miR-124-3p, which suppressed its target CCL2 expression in breast cancer cells, leading to TAMs M2 polarization restraint." (PMID 36038549, 2022). "Based on these data, a strategy aimed at neutralizing CCL2 by specific monoclonal antibodies has been tested in breast cancer models." (PMID 35159113, 2022). "Previous studies have indicated that CCL2 plays a role in pathological processes in breast cancer, ovarian cancer, and cervical cancer." (PMID 36403055, 2022). "CCL2 can also attract inflammatory monocytes to the pulmonary metastasis focuses, allowing breast cancer cells to spread to lung metastases." (PMID 36403055, 2022). "CCL2 is highly expressed in numerous breast cancer lines as well as the monocytes and stroma cells in the tumor microenvironment." (PMID 36403055, 2022). "The authors found that activation of PI3K/AKT and NF-κB induced the upregulation of both PD-L1 and CCL2 in breast cancer cells." (PMID 36077785, 2022). "In a humanized mouse model, elevated CCL2 within the mammary tumor microenvironment enhanced macrophage recruitment, and depletion of macrophages led to decreased blood vessel density and diminished tumor growth." (PMID 35435599, 2022). "CC-chemokine ligand 2 (CCL2) secreted by TAMs was revealed to activate the PI3K/AKT/mTOR pathway in breast cancer cells, thus induced resistance to tamoxifen treatment in breast cancer." (PMID 36151545, 2022). "In studies on breast cancer cells, the relationship between dysadherin and the activity of the CC chemokine (CCL2) has been described, which has a chemotactic effect on monocytes, T lymphocytes and NK cells." (PMID 36012171, 2022). "All these suggest that a CCL2 overexpression improves macrophage infiltration and worsens the prognosis of human breast cancer." (PMID 35911705, 2022). "Altogether, these results suggest that CCL2 leads to tamoxifen resistance and can serve as a novel therapeutic target to overcome tamoxifen resistance in breast cancer patients." (PMID 36077785, 2022). "Tumor cells secrete chemokine (C-C motif) ligand 2 (CCL-2) (lung tumors, breast cancer, cervical cancer, ovarian cancer, etc.)to cause the accumulation of macrophages." (PMID 36081554, 2022). "Our studies demonstrated that MET is important in CCL2/CCR2-mediated breast cancer growth and invasion." (PMID 35405500, 2022). "Studies have revealed that CCL2 improves the survival, motion ability, and migration of mammary carcinoma cell lines 4T1, MCF-7, PyVmT, and MDA-MB-231 by activating phosphorylation of Smad3 and p42/44 MAPK." (PMID 36403055, 2022). "In both the mammary carcinoma and fibrosarcoma cells, secretion of CCL2, CCL3, CCL4, and Cxcl10 was upregulated after poly(I:C) transfection." (PMID 35737804, 2022). "Studies have shown that in breast cancer models, inhibition of CCL2 with anti-CCL2 antibodies decreased both tumor growth and spread." (PMID 34207035, 2021).
breast cancer (continued). "Overall, these studies demonstrate that increased CCL2/CCR2 signaling in breast cancer cells is a physiologically and potentially clinically relevant signature in DCIS progression." (PMID 33888841, 2021). "Steiner and colleagues demonstrated that using bindarit, as a CCL2 synthesis inhibitor, leads to suppression of polyomavirus-related breast cancer development by down-regulation of CCL2 in the tumor tissue, but not in the plasma." (PMID 34082771, 2021). "A high expression of CCL-2 in breast cancer tissue is found to be a significant indicator of early relapse, metastasis, and upregulation of CCL-2 in breast cancer tissue reduces overall survival." (PMID 34944905, 2021). "In mammary tumors, CCL2 induces crosstalk between IL-1β-producing TAMs and γδ T cells, eventually results in immunosuppressive neutrophil entrainment to form a pre-metastatic niche." (PMID 34386431, 2021). "CCL2 production by CAFs, which is often upregulated, has been shown to induce angiogenesis and is associated with the promotion of CSC characteristics in breast cancer." (PMID 34948097, 2021). "Overall, there was little association between CCL2/CCR2 signaling proteins and breast cancer subtype." (PMID 33888841, 2021). "While this has shown promise, in murine breast cancer models, a rebound effect was shown after the withdrawal of anti-CCL2 treatment, increasing the infiltration of bone-marrow monocytes into the tumor and accelerating lung metastasis." (PMID 34209703, 2021). "PyMT+/− female mice fed a CDDO-Me diet demonstrated suppression of TAM infiltration to mammary tumor concomitant with reduced expression of macrophage chemoattractant CCL2 in TAMs compared to the control diet fed mice." (PMID 34207035, 2021). "The chemokine monocyte chemoattractant protein-1 (MCP-1/CCL2) is shown to promote the progression of breast cancer." (PMID 34698088, 2021). "Treatment with anti-CCL2 antibody attenuated metastatic outgrowth and prolonged survival in mouse models of breast cancer metastasis." (PMID 34745140, 2021). "Another chemokine, CCL-5, shows similar abilities as CCL-2 in breast cancer progression, for example, through the attraction of TAMs." (PMID 34944905, 2021). "A high level of CCL2 in primary mammary tumor tissue is the major initiator of the tumor inflammation state via recruitment of inflammatory monocytes and release of IL-1β." (PMID 34386431, 2021). "For example, after radiation, breast cancer cells produce CCL2, which stimulates TAM recruitment and breast cancer cells to modulate tumor survival and invasion." (PMID 34439387, 2021). "CCL2 is a well-known mediator of the innate response and inflammation that supports breast cancer progression through several mechanisms." (PMID 34824220, 2021). "TGF-β1-induced activation of MDA-MB-231 and HCC1937 breast cancer cells led to an increase in the activity of the CCL2 promoter in the luciferase reporter system, and this was fully provided by its − 244/− 1 region." (PMID 34239022, 2021). "Cells of the myeloid lineage, particularly macrophages, comprise the largest immune subpopulations within the ER+ TME, like other breast cancer subtypes, and many clinical ER+ tumors express high levels of macrophage chemoattractants, such as CCL2 and CCL5." (PMID 34359625, 2021). "The expression of CCL2 and the infiltration of the tumor site by macrophages have been correlated with metastatic disease in breast cancer." (PMID 33922795, 2021). "For example, the sensitivity of breast cancer cells to tamoxifen was significantly reduced after culture in media that had been used for TAMs, and addition of CCL2 to the culture medium further reduced the sensitivity of tumor cells to tamoxifen." (PMID 34178692, 2021). "Neoadjuvant chemotherapy was shown to induce release of microvesicles from breast cancer cells containing more CCL2 molecules; it also enhanced infiltration of Ly6C+CCR2+ monocytes recruitment in the lung pre-metastatic site." (PMID 34386431, 2021).
breast cancer (continued). "Recently, research demonstrated that the chemokine CCL2 gene expression level directly correlates with the TGF-β activity in breast cancer patients." (PMID 34239022, 2021). "The expression of CCL2 and CCL5 is associated with inflammation and with advanced breast cancer and tumor progression." (PMID 34228231, 2021). "For instance, the treatment of a neutralizing antibody to CCL2 resulted in a significant reduction in macrophage infiltration, reduced microvessel density, and tumor growth in mouse models of breast cancer." (PMID 33230600, 2021). "Breast cancer cells can use CCL2 in remote organs to recruit MDSCs to build a pre-metastasis niche and promote subsequent metastasis." (PMID 34249913, 2021). "Previously, we demonstrated that CCL2/CCR2 chemokine signaling in breast cancer cell lines regulated growth and invasion through p42/44MAPK and SMAD3 dependent mechanisms." (PMID 33888841, 2021). "CCL2 enhances the migration of multiple breast cancer cell lines via Smad3 and p42/44 mitogen-activated protein kinase (MAPK) signaling." (PMID 34445235, 2021). "Related to cancer treatment, CCL2 significantly reduced apoptosis of mouse and human breast cancer cells induced by gentamicin or 5-FU treatment as determined by cleaved caspase-3 expression." (PMID 34804061, 2021). "When adipocytes are co-cultured with breast cancer cells, cytokines are secreted, specifically IL-8, IL-6, IFNγ-inducible protein 10, CCL2, and CCL5." (PMID 34912237, 2021). "Breast cancer treated with doxorubicin showed promotion of CCL2 production by stromal cells, leading to recruitment of CCR2+ monocytes and contributing to tumor relapse." (PMID 34209703, 2021). "Taken together, these results suggested that tumoral infiltration of TAMs in breast cancer was intensively facilitated by Ldha/Ccl2 signaling pathway in BCSCs." (PMID 34178639, 2021). "Recent studies demonstrated that the CCL2 gene expression level directly correlates with the TGF-β activity in breast cancer patients." (PMID 34239022, 2021). "They found that ALDH1A1 and HTRA2 regulates CCR2‐mediated breast cancer cell growth and cellular invasion in a CCL2/CCR2 context‐dependent manner." (PMID 34708890, 2021). "Similar results were seen in the MMTV-PyMT murine model of luminal B breast cancer, where blocking CCL2 prevented recruitment of TAMs to breast tumors, reduced metastasis, and prolonged the survival of mice." (PMID 33968034, 2021). "Another study demonstrated that polyomaviruses induces expression of CCL2 and CXCL12 to recruit tumor associated macrophages to the polyomavirus-related breast cancer tissue." (PMID 34082771, 2021). "TAM deletion in 3 different ways (CD11b+ TAM deletion, CSF1R mice KO, or clodronate liposomes) and monocyte recruitment inhibition into the lung by CCL2 blockade all inhibit metastatic spread from primary murine PyMT mammary tumor to lungs." (PMID 33783686, 2021). "Recent studies have implicated a role for CCL2 and CCR2 in progression of early stage breast cancers." (PMID 33888841, 2021). "An inhibition of CCL2 signaling was shown to decrease macrophage infiltration and showed anti-tumoral effects in breast cancer." (PMID 33525753, 2021). "Through recruitment of CCR2-expressing monocytes, CCL2 has been shown to promote pulmonary metastasis in mouse models of breast cancer." (PMID 33968034, 2021). "Among these chemokines and cytokines potentially controlled by Wnt/β-catenin pathway, CCL2 has been reported as a target of the β-catenin/TCF/LEF pathway in breast cancer and plays a vital role in stimulating tumor progression and metastasis." (PMID 33924999, 2021). "The expression of CCL2 in breast cancer in conjunction with the infiltration of CCR2-expressing inflammatory macrophages is correlated with poor prognosis and metastatic human breast cancer." (PMID 34063828, 2021).
breast cancer (continued). "IL-6, IL-8, CCL2, and CCL5 have been found to be stimulators of the proliferation, survival, and invasion of breast cancer cells and are linked to an advanced stage of breast cancer." (PMID 34912237, 2021). "In fact, the chronic hepatitis B therapeutic drug propagermanium is currently being studied as a treatment option for breast cancer because of its inhibitory action on CCL2." (PMID 34445235, 2021). "CCL2 secreted by CAFs activates the NOTCH1 pathway that further induces CSC phenotype in the breast cancer cells, granting them self-renewal potential, indicating CCL2 as a potential target to block non-CSC-to-CSC switch." (PMID 34262865, 2021). "We confirmed miR-200c-dependent upregulation of GM-CSF (CSF2), CXCL10, and CCL2 after transient transfection of miR-200c mimic compared to scramble (Scr) control in mouse mammary carcinoma and human TNBC cells." (PMID 34045467, 2021). "Neutralization of CCL2 also inhibits chemotaxis of human endothelial cells, increases survival and inhibits lung metastases in mice bearing human breast carcinoma cells.Tumor metastasis involves epithelial-mesenchymal transition (EMT)." (PMID 34804061, 2021). "Doxorubicin and paclitaxel treatment results in the recruitment of innate immune cells and CSF1R-dependent macrophages infiltration in PyMT-MMTV mammary carcinoma through an increase of CCL2, CXCL2, CSF-1, interleukin-34 and vascular permeability." (PMID 34283088, 2021). "Analysis of published datasets found that the coexpression of S100A14 and CCL2/CXCL5 in breast cancer tissues is a significant determinant of poor metastasis-free survival for breast cancer patients." (PMID 32483412, 2020). "We have observed that CCL2 and, to some extent, P65 expression are higher in breast cancer patients from the METABRIC dataset." (PMID 32455851, 2020). "Adipose stroma cell-derived IL-6, oncostatin M (OSM), and C-C motif chemokine ligand 2 (CCL2) have been shown to promote breast cancer cell proliferation, migration and invasion." (PMID 32242230, 2020). "Although a great number of the studies focusing on the function of CCL2 in cancer progression used prostate and breast cancer cells, more recent CCL2 studies have incorporated colorectal, lung, gynecological, gastric, and other types of cancer cells." (PMID 33297571, 2020). "Breast cancer is associated with increased CCL7 expression, while glioblastoma multiforme is accompanied by increased concentrations of CCL2 and CCL7." (PMID 33182504, 2020). "In breast cancer, inflammatory monocytes can be continually recruited by CCL2 produced by cancer cells and differentiate into TAMs that facilitate the subsequent growth of metastatic cells." (PMID 32653013, 2020). "Breast cancer patients with high CCL2 expression in their tumor cells possessed a shorter RFS, and for clear cell renal cell cancer patients, elevated CCL2 expression was correlated with clinical stage, OS, and macrophage infiltration." (PMID 32429318, 2020). "Our work is consistent with a prior report that Twist1 transcriptionally induces Ccl2 in breast cancer cell lines that leads to macrophage recruitment." (PMID 31933479, 2020). "CCL2/CCR2 chemokine signaling was demonstrated to promote breast cancer progression by inducing angiogenesis." (PMID 33099574, 2020). "Analysis of 151 breast cancer samples showed that high expression of CCL2 and vascular endothelial growth factor were a significant indicator of early recurrence of breast cancer." (PMID 33297571, 2020). "As reported by Pollard’s group, blocking CCL2/CCR2 interaction effectively inhibited the recruitment of metastasis-associated macrophages and inhibited breast cancer metastasis." (PMID 32993785, 2020). "CCL2 is upregulated following RB inactivation in human breast cancer cells, not only in mouse sarcoma cells." (PMID 32244804, 2020). "TAM infiltration is associated with the expression of the chemoattractants CCL2 and CCL5, which are influenced by E2 in breast cancer." (PMID 32133288, 2020).
breast cancer (continued). "RB depletion in breast cancer cells increased production of multiple cytokines and chemokines, including IL-6 and CCL2." (PMID 32244804, 2020). "In vivo, production of CCL2 by metastatic breast cancer cells has been shown to increase recruitment of inflammatory monocytes." (PMID 33069212, 2020). "In the present study, we identified S100A14 as a novel upstream regulator of CCL2, administration of CCL2 blocking antibody led to decreased breast cancer metastasis, providing an alternative strategy for targeting the CCL2 signaling pathway." (PMID 32483412, 2020). "These evidences suggest that CCL2 is an important molecule during both mammary gland development and breast cancer progression." (PMID 33244467, 2020). "Taken together, CCL2 is a promising target for inhibiting breast cancer metastasis; however, the role of brazilin in metastasis-related to CCL2 and TNFα signaling needs to be explored further." (PMID 32986377, 2020). "For example, CCL2/CCR2 chemokine signaling has been overactive in several cancers, including breast cancer, and has been associated with poor prognosis." (PMID 33024416, 2020). "Here, we use the HIM model to examine inflammation induced by CCL2, which is significantly increased in obese adipose tissue, and the consequences within developing mammary tumors." (PMID 32731354, 2020). "Immunohistochemistry to examine the frequency of TAMs and CCL2-expressing cells from paraffin blocks of 137 breast cancer patients found that high frequency of CCL2 positive cancer cells and CD14+ TAMs were significant risk factors for cancer recurrence." (PMID 33297571, 2020). "Mechanistic studies demonstrated that S100A14 promotes breast cancer metastasis by upregulating the expression and secretion of CCL2 and CXCL5 via NF-κB mediated transcription." (PMID 32483412, 2020). "Previous evidence from breast cancer studies shows that CCL2 can be downstream of ERα to interact with macrophages, and we further prove that the regulation is through a transcriptional regulation of the CCL2 promoter." (PMID 32356397, 2020). "In breast cancer, based on the tumor type, MDSCs are recruited to the tumor sites by various chemokines including CCL2, CXCL5, and CXCL12 (SDF-1)." (PMID 32726950, 2020). "Mammary tumors were collected after 10 weeks when tumors that formed in SVF/CCL2 humanized mammary glands reached 1 cm in diameter (end-stage)." (PMID 32731354, 2020). "The CCL2/CCR2 axis in breast cancer is known to be involved in the metastatic process via the recruitment of different myeloid cell subsets, including TAMs and the induction of angiogenesis." (PMID 32225066, 2020). "The expression of cytokines (e.g., C-C motif chemokine ligand 2 (CCL2)) that facilitate mammary tumor metastasis was also examined using tumor-free and 4T1-mCh tumor-bearing Rag1−/− mice." (PMID 33628730, 2020). "PARP1 knockdown and PJ34 mediated inhibition showed reduced CCL2 transcript levels in breast cancer cells, corroborating the findings from the sequencing data." (PMID 32455851, 2020). "The necessity of CCL2 for mobilization of endothelial progenitor cells was demonstrated in a genetic murine breast cancer model, exhibiting reduced numbers of these cells in the blood in Her2/neu CCL2-deficient mice." (PMID 31690961, 2020). "Breast cancers, particularly TNBCs, show upregulation of CCL2 and overall PARylation with positive feedback controlling CCL2 expression and PARP1 activity." (PMID 32455851, 2020). "In parallel, CCL2 was found to be expressed at the site of metastatic breast cancer localization in the bones and breast cancer-derived CCL2 has acted through CCR2 to promote osteoclast differentiation and contributed to bone metastasis." (PMID 32582148, 2020). "Specifically, CCL2 production was impacted by the loss of CD44 in both the Hs578T and MDA-MB-231 cells, which is relevant to breast cancer, as CCL2 has been shown to recruit monocytes into the primary tumor and promote metastasis." (PMID 32455980, 2020).